CADPS (calcium dependent secretion activator)
Description:
Calcium-binding protein involved in exocytosis of vesicles filled with neurotransmitters and neuropeptides. Probably acts upstream of fusion in the biogenesis or maintenance of mature secretory vesicles. Regulates catecholamine loading of DCVs. May specifically mediate the Ca(2+)-dependent exocytosis of large dense-core vesicles (DCVs) and other dense-core vesicles by acting as a PtdIns(4,5)P2-binding protein that acts at prefusion step following ATP-dependent priming and participates in DCVs-membrane fusion. However, it may also participate in small clear synaptic vesicles (SVs) exocytosis and it is unclear whether its function is related to Ca(2+) triggering (By similarity).
Synonyms: CAPS; CAPS1; KIAA1121; UNC-31; CADPS1
Tractability: Antibody: UniProt places it where antibodies can reach, with medium confidence. PROTAC: its protein half-life has been measured.
Gene: Protein-coding gene on chromosome 3 (62,398,346 to 62,875,563, reverse strand). Ensembl gene ENSG00000163618.
Subcellular location: Synapse; Cytoplasmic vesicle, secretory vesicle, neuronal dense core vesicle membrane
Subcellular location (Human Protein Atlas): Vesicles
Gene Ontology:
Molecular function: protein binding; protein kinase binding
Biological process: exocytosis; positive regulation of exocytosis; dense core granule exocytosis; synaptic vesicle exocytosis
Cellular component: cytosol; glutamatergic synapse; synapse; neuronal dense core vesicle membrane; presynapse
Genetic constraint (gnomAD): Loss-of-function variants: 37 observed, 109.3 expected, observed/expected ratio (o/e) 0.34, 90% interval 0.26 to 0.44. The upper end of that interval is the gene's LOEUF score, 0.44, which puts it in group 1 of 6, group 1 being the genes least tolerant of losing a copy. Missense variants: 1,048 observed, 1,348.7 expected, observed/expected ratio (o/e) 0.78, 90% interval 0.74 to 0.82. Synonymous variants: 516 observed, 496.33 expected, observed/expected ratio (o/e) 1.04, 90% interval 0.97 to 1.12.
Diseases named in the same sentence as CADPS in open-access papers:
CADPS is named in the same sentence as 22 diseases in open-access papers, as found by Europe PMC text mining. Sharing a sentence is not in itself a finding about the gene and the disease. The quoted sentences say what the papers report.
breast carcinoma (2 papers, 2016 to 2025). "CADPS is down-regulated in many types of tumors, although it has not been reported as associated to breast cancer." (PMID 27895661, 2016).
celiac disease (1 paper, 2023). An autoimmune genetic disorder with an unknown pattern of inheritance that primarily affects the digestive tract. "In humans, the increased expression of CADPS within immune cells has been shown to modulate inflammatory responses of intestinal endothelium during chronic inflammation, which is characteristic of celiac disease." (PMID 37685039, 2023).
cholangiocarcinoma (1 paper, 2025). A carcinoma that arises from the intrahepatic biliary tree (intrahepatic cholangiocarcinoma) or from the junction, or adjacent to the junction, of the right and left hepatic ducts (hilar cholangiocarcinoma). "Although no studies to date have shown that CADPS modulates chemoresistance or apoptotic pathways in leukemia cells, research in cholangiocarcinoma has demonstrated that CADPS is downregulated and associated with poor prognosis." (PMID 40454861, 2025). "Specifically, CADPS downregulation has been observed in high-grade serous ovarian cancer, cholangiocarcinoma, and hepatocellular carcinoma, suggesting a conserved tumor-suppressive function across malignancies." (PMID 40454861, 2025).
colon carcinoma (1 paper, 2013). "Recently, CADPS has been detected to harbor mutation p.R722W and p.R787* in colon carcinoma." (PMID 23658834, 2013).
diabetes (1 paper, 2024). "Multiple machine learning algorithms identified 4 shared biomarkers for COPD and diabetes, including CADPS, EDNRB, THBS4 and TMEM27." (PMID 39845878, 2024). "As expected, CADPS was observed to be highly expressed in macrophages and significantly increased in diabetic patients, making it a robust biomarker for diabetes patients." (PMID 39845878, 2024). "Ultimately, we conducted a cross-analysis of the 4 potential biomarkers gene sets and 4 genes as shared biomarkers for COPD and diabetes, including CADPS, EDNRB, THBS4 and TMEM27." (PMID 39845878, 2024). "In this study, we integrated microarray data from multiple cohorts of COPD and diabetes patients, and comprehensively utilized various machine learning algorithms to identify shared biomarkers in COPD and diabetes patients, including CADPS, EDNRB, THBS4 and TMEM27." (PMID 39845878, 2024). "In this study, we observed that the expression level of CADPS is abnormally increased in diabetic patients, leading to the disruption of metabolic balance in pancreatic β cells and participating in the pathogenesis of diabetes." (PMID 39845878, 2024). "For instance, exploring how CADPS modulates β-cell function in diabetes or immune cell activation in COPD through in vitro and in vivo experiments could clarify its functional relevance." (PMID 39845878, 2024). "Based on microarray data of multi-center COPD and diabetes patients, the gene expression analysis results showed that CADPS and TMEM27 were significantly upregulated in both COPD and diabetes, while EDNR8 and THBS4 were significantly downregulated." (PMID 39845878, 2024). "While this study provides compelling evidence for the role of CADPS, EDNRB, THBS4, and TMEM27 as shared biomarkers between COPD and diabetes, it is important to acknowledge that the specific molecular mechanisms underlying their involvement in disease progression remain incompletely understood." (PMID 39845878, 2024).
mastitis (1 paper, 2023). Inflammation of breast tissue during lactation or postpartum due to an obstructed duct or infection. "Another association signal for mastitis among LZG cows was located within the intron of CADPS." (PMID 37685039, 2023).
pancreatic cancer (1 paper, 2022). "For example, NOP14 promoted proliferation and metastasis of pancreatic cancer cells, and loss of CADPS was associated with poor prognosis of malignant embryonal brain tumors." (PMID 35406793, 2022).
tumor (5 papers, 2014 to 2025). "Conversely, B3GNT1, NOSTRIN and CADPS followed a reverse trend with down-regulation associated with poor outcome, thus suggesting a tumour suppressor role." (PMID 25587357, 2014). "Among the differentially expressed genes, calcium-dependent activator protein for secretion (CADPS) emerged as a key candidate due to its marked downregulation in the recurrence group and its previously reported tumor-suppressive roles in other cancers." (PMID 40454861, 2025). "Significant upregulation of expression is found in genes associated with tumor cell invasion such TGFβ1, ROAR, DAB2, BMP6, NOS2, PLXN2, and CADPS, whereas TCF4 was significantly downregulated in AHCY deficient cells." (PMID 38003292, 2023). "Also, significant alterations in genes associated with tumor cell invasion were detected, such as significant upregulation of TGFβ1, ROAR, DAB2, BMP6, NOS2, PLXN2, and CADPS exhibited, and significant downregulation of TCF4." (PMID 38003292, 2023). "TENM4 and ACSM3, as well as CADPS and SLC35F3, were highly expressed in clusters 5 and 13, respectively, which represented two different sub-clusters in the tumor–stroma interface area." (PMID 38473208, 2024). "Finally, CADPS, a novel neural and endocrine-specific cytosolic protein required for the Ca2+-regulated exocytosis of secretory vesicles, was highly expressed by HGSOC cells particularly in the tumor–stroma interface." (PMID 38473208, 2024).
cancer (2 papers, 2019 to 2025). A tumor composed of atypical neoplastic, often pleomorphic cells that invade other tissues. "A few recoding sites are highly edited in GBM compared to the normal brain with the top positions being COG3 I/V and CADPS E/G (with > 15% editing increase in cancer)." (PMID 30760294, 2019). "Despite the global editing loss observed in GBM, we found that a few recoding sites (12 sites) were over-edited in cancer, with the top sites being CADPS E/G (+ 17% Δ medians) and COG3 I/V (+ 17% Δ median)." (PMID 30760294, 2019). "CADPS, also known as CAPS1, plays a critical role in the progression of various malignant tumors." (PMID 40454861, 2025).
infection (2 papers, 2019 to 2022). The state of being infected such as from the introduction of a foreign agent such as serum, vaccine, antigenic substance or organism. "In addition, four T. spiralis proteins were found both 4 and 8 weeks after infection, namely hypothetical protein T01_16145 (KRY36525.1), conserved hypothetical protein (XP_003366234.1), calcium-dependent secretion activator 1 (XP_003375206.1) and protein CLEC16A (KRY38014.1)." (PMID 35271623, 2022).
CADPS also shares sentences with these, for which no sentence is quoted: acute lymphoblastic leukemia (1 paper); colorectal cancer (1); heart failure (1); hepatocellular carcinoma (1); keratoconus (1); leukemia (1); lung carcinoma (1); medulloblastoma (1); Osteochondrosis (1); ovarian carcinoma (1); Seizure (1); serous ovarian cancer (1).